EGFR (epidermal growth factor receptor)
Diseases named in the same sentence as EGFR in open-access papers (continued):
Sharing a sentence is not in itself a finding about the gene and the disease.
tumor (continued). "Whole tumor single-cell RNA sequencing (scRNA-seq) analysis and blockade experiments revealed that the amphiregulin (AREG)–epidermal growth factor receptor (EGFR) axis mediated cross-talk between IL1RL1+ Treg cells and CAFs." (PMID 37611111, 2023). "The main groups of Mabs in SCC therapy are Mabs targeting EGFR, HER2, HGF, and VEGF, alongside checkpoint inhibitors (including Mabs to PD‐1, CTLA4, and NKG2A) and tumor targeting Mabs." (PMID 37042307, 2023). "After being treated to NSCLC tumor-bearing in vivo models, the EGFR-targeting PROTAC exhibited a better tumor growth suppression effect than gefitinib, promoting the migration of CD3-positive T cells to tumor tissues." (PMID 36839734, 2023). "KNE infection was selective for EGFR-overexpressing cells in vitro and inhibited GSC-derived tumor growth in immunodeficient mice." (PMID 37325516, 2023). "Inactivation of many genes that were functional tumor suppressors in KRAS-driven lung tumors, including Lkb1, Setd2, and Kmt2d, were deleterious in EGFR-driven lung tumors." (PMID 37828026, 2023). "The EGFR TKI survival benefit positively correlated with tumor-tumor interaction image features and negatively correlated with tumor-stroma interaction." (PMID 36647832, 2023). "The choice of the moAb lies between drugs directed against the epidermal growth factor receptor (EGFR) and the vascular endothelial growth factor receptor (VEGFR), according to the patient characteristics, tumor molecular profile, and primary tumor location." (PMID 36982913, 2023). "The expression levels of mesenchymal and epithelial markers, EMT-related transcription factors, MMPs, p-HER2, p-EGFR and p-ERK1/2 were then detected in xenograft tumor tissues." (PMID 36656313, 2023). "It has been suggested that the efficacy of EGFR-TKIs depends mainly on the presence of CD4+ and CD8+ T cells, as treatment significantly enhances the immune responses against the tumor." (PMID 37601668, 2023). "In this study, we aimed to validate the anti-tumor effect of β2-AR blockade and the synergism with MEK/ERK and EGFR pathway inhibition in a pre-clinical orthotopic mouse model of HNSCC." (PMID 37723219, 2023). "Brains from the mice IT-injected with PC9 BrM3-GFl cell line were then harvested and tested for the upregulation of EGFR, DR4, and DR5 in the tumor area." (PMID 37311043, 2023). "The results revealed that the NSCLC patients who harbored EGFR mutations or ALK rearrangements are associated with low objective response rates to anti-PD-1/PD-L1 therapy, which may be due to low rates of co-localized PD-L1 expression and CD8(+) tumor-infiltrating lymphocytes (TILs)." (PMID 37465684, 2023). "miR-128 reduces tumor cell growth by targeting PDGFRA and EGFR and controls angiogenesis by inhibiting P70S6K1 kinase." (PMID 37371047, 2023). "The efficacy of EGFR/COX-2 dual inhibition has been reported in several cancer cell models and animal models of different tumor types." (PMID 37190301, 2023). "It was further found that targeting EGFR and CD44 synergistically mediated the erastin-induced tumor inhibition of cancer stem cell clusters in TNBC." (PMID 37174125, 2023). "Phosphorylation of EGFR was significantly inhibited by combined treatment with BBR and erlotinib in tumor samples obtained from mice." (PMID 37170144, 2023). "Thus, patients with tumours resistant towards anti-EGFR treatment may benefit from VEGF inhibition." (PMID 37666855, 2023). "Very recently published preclinical data suggest augmented antitumoral activity using in vivo models of the dual targeting of EGFR and MET in this particular tumor type." (PMID 37370859, 2023). "EGFR promoted TNBC cell clustering, and the blockade of EGFR successfully abolished tumor cell cluster formation." (PMID 37681908, 2023). "EGFR activation promotes dimer PKM2 expression and nuclear translocation to activate HIF-1α, contributing to abnormal glycolysis and tumor cell proliferation." (PMID 36874012, 2023).
tumor (continued). "The anti-tumor effects of KAN0441571C alone were evaluated in vitro and in combination with erlotinib (EGFR inhibitor) and ibrutinib (BTK inhibitor)." (PMID 37111634, 2023). "Previous studies showed that FBXW2 functions as putative tumor suppressor in many cancers through directing proteasomal degradation of several oncogenes including SKP2, β-catenin, and EGFR." (PMID 37736741, 2023). "HIF-1 can also induce the expression of the epidermal growth factor receptor (EGFR), transforming growth factor-β, insulin-like growth factor 2 to promote tumor angiogenesis." (PMID 37693915, 2023). "Bevacizumab-800CW, cetuximab-800CW and SGM-101, targeting, respectively, VEGF-A, EGFR, and CEA, are currently being investigated for the detection of resection margins of the primary tumour and (lymph node) metastases." (PMID 37721591, 2023). "In the hypoxic tumor microenvironment, the transcriptional regulation of HIF1A mediates the upregulation of PLOD2, which can activate EGFR phosphorylation, thereby activating the downstream AKT-mTOR pathway and ultimately promoting ccRCC tumor progression." (PMID 38008826, 2023). "Antibody-cytokine fusion proteins, such as anti-CD20/IFN-α, SumIL2/anti-EGFR, an-ti-PD1/IL-21, anti-EGFR/IL-21, arose to target these molecules in the tumor environment and demonstrated an improvement in either increased antitumor efficacy or reduced toxicity." (PMID 37047449, 2023). "This combination demonstrated promising preliminary anti-tumor activity in patients with MET-amplified advanced NSCLC, who experienced progression on prior first-, second-, or third-generation EGFR-TKIs38,39." (PMID 36849494, 2023). "According to previous studies, CAR-T cells targeting EGFR, HER2, etc., demonstrate anti-tumor efficacy and show promising clinical responses." (PMID 36983174, 2023). "By sustaining EGFR/CDK2 activity and by being expressed at such high levels in this tumor entity, EMP3 provides an additional level of resistance that protects tumor cells from targeted kinase inhibitors." (PMID 37936247, 2023). "In this study, we identify TMEM25 as an EGFR binding protein to prevent monomeric EGFR-mediated phosphorylation of STAT3 in the basal state, therefore functioning as a tumor suppressor to inhibit TNBC progression." (PMID 37095176, 2023). "The EGFR system and HER-2/neu both appear to be crucial in the control of tumor development and angiogenesis, since such expression has been linked to a negative prognosis for patients." (PMID 36902446, 2023). "As a proof-of-principle study, we translated this mechanism to the treatment of OSCC tongue orthotopic xenografts and EGFR-positive PDX models by NP-delivered siLCN2, which effectively inhibited tumor progression and cervical lymphatic metastasis." (PMID 36899380, 2023). "The differential mRNA expression analysis of genes included in the AVENIO surveillance panel demonstrated that MET, EGFR, SLPI, and TNFRSF21 had the highest difference in log2(TPM + 1) between NSCLC tumours and PBMCs." (PMID 36825535, 2023). "Co-treating patient and transgenic mouse lung-tissue-derived tumour organoids with AICAR and JAK1 and EGFR inhibitors reduced their growth." (PMID 36810913, 2023). "HPK uses the human epidermal growth factor receptor ErbB3 (HER3) to target bioparticles to tumor cells and induce tumor cell entry." (PMID 37370850, 2023). "In P03 and P50, EGFR amplification was found with KDD in afatinib‐treated and erlotinib‐treated tumor tissue samples, respectively." (PMID 36325957, 2023). "Therefore, targeting EGFR and its downstream signaling, in combination with PD-1/PD-L1 ICIs, may hold the potential in restoring the T-lymphocyte killing capacity and improving the sensitivity to immunotherapy and targeted therapy in tumor patients." (PMID 37601668, 2023).
tumor (continued). "In addition, overexpression of EGFR may be lost after LADC tumor cells have migrated to the brain." (PMID 36527824, 2023). "EGF production by tumor-infiltrating M2 TAMs within the TME can stimulate the NF-κB, STAT3, EGFR, and extracellular signal-regulated kinase signaling axes in tumor cells, promoting their invasive traits." (PMID 38033495, 2023). "Epiregulin (EREG) is a ligand of epidermal growth factor receptor (EGFR), which is involved in RAS-RAF-MAPK and PI3K-AKT-mTOR signaling pathways regulating tumor proliferation, invasion, and migration." (PMID 36874096, 2023). "The upregulation of SPP1 due to hypermethylation induces resistance to the 1st and 2nd generation EGFR-TKI and influences tumor immune infiltration in tumor tissues and cell lines." (PMID 37152062, 2023). "Additionally, the tumor suppressor potential of MIAC was recently demonstrated in renal cell carcinoma where MIAC overexpression inhibited tumor growth of renal cancer cells in a subcutaneous xenograft mouse model by inhibiting epiregulin/epidermal growth factor receptor signaling." (PMID 37213226, 2023). "This list of driver genes, however, was not particularly comprehensive, because other studies have also identified a broad spectrum of gene abnormalities in OSCC that are likely to contribute to tumour development and progression (FAT1, EGFR, CCND1)." (PMID 36671795, 2023). "As for EGFR-mutant NSCLC patients, tyrosine kinase inhibitors (TKIs) are milestones of tumor-targeted therapy, which have greatly improved the outcomes." (PMID 37388902, 2023). "In experimental models, oligoclonal cocktails of three to six antibodies against EGFR, HER2 and HER3 increased the anti-tumor effect with blockade of the intracellular ERK and AKT signaling pathways and accelerated receptor degradation." (PMID 37153618, 2023). "Recently, targeted therapies (e.g., antibodies against c-Kit, EGFR, VEGFR, ErbB2/HER-2) have been introduced when tumour-specific targets are available." (PMID 36975417, 2023). "Patient 18 underwent several TKIs and EGFR KDD was identified in plasma and tumor tissue after afatinib treatment." (PMID 36325957, 2023). "Clinical studies have found that the tumor immune microenvironment is altered after receiving EGFR-TKIs targeted therapy, including an increase in CD8+ tumor-infiltrating lymphocytes (TILs) density, TMB, and PD-L1 expression in tumor cells." (PMID 37869096, 2023). "In Drosophila wing disc tumor cells, we have recently shown that EGFRAP restrain the oncogenic capacity of EGFR/Ras hyperactivation." (PMID 37510408, 2023). "EGFR is a transmembrane glycoprotein belonging to the ERBB receptor tyrosine kinase family, that is involved in tumor growth and metastatization." (PMID 36900394, 2023). "The probability of interaction between tumor cells and fibroblast receptor-ligand pairs was higher than that of thyroid cells, especially in TGFB1/ACVR1/TGFBR1, FGF18/FGFR1, BTC/EGFR, BMP8A/BMPR1A/BMPR2, and BMP8A/BMPR1A/BMPR2." (PMID 37733241, 2023). "The aim of this study was, therefore, to investigate and compare the histopathological response of the primary tumor to the addition of VEGF and EGFR antibodies to systemic therapy prior to the resection of the primary and liver metastases." (PMID 37296862, 2023). "The stimulation with both growth factors ensures that both signalling pathways initiated from EGFR and MET receptors are activated, which mimics physiological conditions in the tumour microenvironment." (PMID 37679999, 2023). "Tarloxitinib-E has been shown to directly inhibit the phosphorylation and activation of EGFR, HER2 and HER2/HER3 heterodimers in vitro, resulting in tumor regression in vivo." (PMID 36831628, 2023). "Among the identified interactions, we suggest EDN1/EDNRB as a putative novel tumor/endothelial cell interaction, and ANG/PLXNB2 and ANG/EGFR as putative new autocrine loops in ccRCC cancer cells." (PMID 38025776, 2023).
tumor (continued). "One approach is tumor-targeting, covering both heme malignancies (CD19) and solid tumors (PD-L1, Her2, FAP, EGFR, PSMA, Cldn18.2, Nectin 4, B7H4, CEACAM5, 5T4, EphA2)." (PMID 37662949, 2023). "In this study, we embarked on the pursuit of identifying differentially expressed genes (DEGs) between EGFR–TKI-sensitive and acquired drug-resistant NSCLC xenograft tumor samples." (PMID 37816585, 2023). "Here, the authors describe a quantitative functional cancer genomics platform in genetically engineered mice, and uncover complex interactions between tumor suppressors and KRAS, BRAF, and EGFR oncogenes across more than 100 different lung tumor genotypes." (PMID 37828026, 2023). "The models showed characteristic copy number variations (CNV) of disease-related genes (e.g., MDM4, EGFR, CDKN2A, CDK4, and MDM2) that were fairly consistent with the primary tumor." (PMID 37508520, 2023). "More than 60% of NSCLC tumors overexpress epidermal growth factor receptor (EGFR), which is correlated with tumor malignancy and poor prognosis." (PMID 37762316, 2023). "Patients (~15%) diagnosed with EGFR-mutant NSCLC have a good initial clinical response to epidermal growth factor receptor (EGFR) tyrosine kinase inhibitors (EGFR TKIs), but tumor recurrence is common and quick to develop." (PMID 36961882, 2023). "It has been demonstrated that EGFR and JNK signaling can promote growth and proliferation in many cell types, and genetic hyperactivation of both signaling pathways can drive tumor formation." (PMID 36831328, 2023). "Recent studies indicated that combined inhibition of EGFR and CRAF in KRAS-driven models of PDAC prevented tumor development; therefore, there is a growing interest in targeting CRAF as a strategy to treat KRAS mutant tumors." (PMID 37996408, 2023). "In vitro and in vivo studies showed significant synergistic effects when using EGFR DTX/RSV LPNs, higher tumor inhibition ability, and the lowest systemic toxicity." (PMID 37754880, 2023). "In this study, we identified PLCD1 as a functional TSG downregulated by promoter CpG methylation in RCC, and it exerts tumor suppressor effects by blocking WNT/β-catenin and EGFR-FAK-ERK signaling." (PMID 36849889, 2023). "Based on this limited evidence, we retrospectively compared the efficacy of third-line therapy with anti-EGFR-based treatment versus R/T in RAS/BRAF wt mCRC patients, according to the primary tumor site." (PMID 36895480, 2023). "Treatment with zenocutuzumab has been shown to decrease phosphorylation of HER2, HER3, EGFR, and HER4 and reduce NRG1 fusion-dependent oncogenic signaling, thereby suppressing tumor growth in preclinical models." (PMID 36831628, 2023). "In Cluster2, the up-regulated gene sets included growth receptors such as EGFR, TGFBR2, and GHR, as well as tumor suppressor genes found in apoptotic gene sets." (PMID 37226243, 2023). "It has been reported that Smurf2 appears to act as an oncogene, promoting tumor development through stabilization of KRAS and EGFR." (PMID 36611161, 2023). "Eckol, a novel natural phizolian derived from marine brown algae, has been shown to downregulate EGFR, p-EGFR, JAK2, and STAT3 expression in tumor cells, indicating pro-apoptotic and anti-proliferative activities." (PMID 37859983, 2023). "Through various tumor-specific analyses, we show that PRV-LAV infects cancer cells via the NRP1/EGFR signaling pathway, which is commonly overexpressed in cancer." (PMID 37891570, 2023).
tumor (continued). "FUT8 catalyzes the addition of fucose unit to the GlcNAc at the end of N-glycans to form core fucosylation, which promotes tumor invasion and migration by regulating downstream pathways, such as TGF-β, EGFR, and Wnt/β-catenin." (PMID 35752750, 2022). "Consistent with the findings that identified SCAMP3 as a tumor-promoting protein, our results indicated that SCAMP3 plays a significant role in the oncogenesis and progression of TNBC through the regulation of EGFR degradation and other multiple pathways." (PMID 35681787, 2022). "Western blot analysis of tumor tissues showed that COL8A1 knockdown reduced IFIT1 and IFIT3 expression, as well as EGFR phosphorylation." (PMID 35280763, 2022). "At the cellular level, EGFR mRNA expression was shown to be deregulated in CRLM compared to the primary tumor, and CRC cells overexpressing EGFR showed a metastatic phenotype, suggesting that EGFR plays an important role in CRLM." (PMID 35565214, 2022). "It is now recognized that the FGFR3 signaling pathway overlaps with some oncogenic pathways in the human body, including the EGFR/RAS/PI3K/ERK/AKT pathway, and is correlated with the epithelial-to-mesenchymal transition of tumor." (PMID 35991125, 2022). "A similar tumor-growth-inhibition-model-based approach has been reported for PRO95780 (anti-DR5 antibody), rhuMAb VEGF (anti-VEGF antibody), SI-B001 (anti-EGFR/HER3 bispecific antibody), and MCLA-128 (anti-HER2/HER3 bispecific antibody)." (PMID 35631335, 2022). "The relationship between EGFR/TRAF4 signaling and tumor proliferation was established based on experiments with tumor cell lines." (PMID 35748027, 2022). "Collectively, our data imply that the emergence of TRAF4 allows EGFR activation to engage the MEKK3‐ERK5 axis, promoting tumor formation through the induction of genes critical for cell proliferation." (PMID 35748027, 2022). "EGFR was positively upregulated by the epigenetic complex, p300/YY1, in a manner dependent on CRNDE expression, leading to enhanced tumor cell proliferation and sorafenib resistance." (PMID 35999564, 2022). "The inhibitory effect of PTS on the in-tumor mTOR pathway resulted in the downregulation of TGF-β, CD44, VEGF, and EGFR, which would have had the effect of retarding tumor-cell migration and invasion, thus reducing the potential risk of metastasis." (PMID 36077992, 2022). "previously prepared an EGFR-targeting ADC (LR004-VC-MMAE), which exhibited favorable anti-tumor activity in mouse models of EC." (PMID 35416106, 2022). "Studies have demonstrated that EGFR-targeting MNPs under the action of AMF can selectively induce LMP in EGFR-overexpressing tumor cells and kill tumor cells." (PMID 36359744, 2022). "As a multiple target TKI, all the target molecules (e.g., VEGFR 1 to 3, EGFR, PDGFR-α and -β and FGFR 1–3) of anlotinib can contribute to its inhibitory action on tumor angiogenesis and affect tumor cell growth function." (PMID 35431969, 2022). "Like HER2, the EGFR promotes CSC-like activity and tumor progression by activation of pro-inflammatory signaling." (PMID 35646668, 2022). "We previously established a defucosylated mouse-dog chimeric anti-EGFR mAb (E134Bf) and a mouse-dog chimeric anti-HER2 mAb (H77Bf), which exerted antitumor activities in canine tumor xenograft models." (PMID 36432687, 2022). "As we all know, the epidermal growth factor receptor (EGFR) gene was changed in approximately 10%∼15% of NSCLC, which played an essential role in tumor progression." (PMID 35935840, 2022). "Moreover, we also found that the patients who underwent tumor resection within 6 months after the initiation of EGFR-TKI treatment had better PFS and a lower proportion of co-existing genomic alterations, which might imply the potential benefit of early surgical intervention." (PMID 36581631, 2022). "Decorin has mostly been known for its tumor-suppressor functions through TGF-β and EGFR-mediated signaling and was previously found to be downregulated in PCa." (PMID 36230789, 2022).